INS (insulin)
Diseases named in the same sentence as INS in open-access papers (continued):
Sharing a sentence is not in itself a finding about the gene and the disease.
Hyperinsulinemia (continued). "Genetic predisposition, sustained excessive calorie intake (due to overnutrition), a Western dietary pattern, the consumption of food additives, and reduced hepatic insulin clearance may all contribute to fasting and postprandial hyperinsulinemia." (PMID 39769002, 2024). "Interestingly, elevated tau levels in T2DM patients paradoxically enhance insulin secretion, potentially contributing to hyperinsulinemia." (PMID 39596023, 2024). "In hyperinsulinemia, elevated insulin levels indirectly promote tumorigenesis." (PMID 39290325, 2024). "Thus, impaired central insulin signaling enhanced by hyperinsulinemia and insulin resistance affects neuronal and synaptic functioning, thereby impairing memory and learning processes." (PMID 39684351, 2024). "IR prompts an elevation in serum insulin level, leading to hyperinsulinemia." (PMID 39376609, 2024). "The relationship between the dietary insulin index (DII) and the disease’s risk is unknown, despite the fact that hyperinsulinemia is presumed to contribute to osteoporosis." (PMID 39004741, 2024). "Consequently, pancreatic β-cells compensate for the increased blood glucose concentrations by releasing a substantial amount of insulin to decrease the heightened glucose concentrations, leading to compensatory hyperinsulinemia." (PMID 38612885, 2024). "There is also some evidence that hyperinsulinemia accelerates the metabolic clearance of C-peptide, which may lead to a decrease in endogenous C-peptide-based insulin secretion." (PMID 38921478, 2024). "In hyperinsulinemia, there are insulin pathways which are highly responsive to insulin." (PMID 38397072, 2024). "Fourthly, ATP surplus may induce endocrine disorders such as hyperinsulinemia and hyperglucagonemia to impair systemic insulin sensitivity." (PMID 39873003, 2024). "According to the findings of some research, insulin hypersecretion and postprandial hyperinsulinemia may eventually develop in insulin resistance (IR), which may then benefit bone mineral density (BMD)." (PMID 39004741, 2024). "Hence, while insulin is essential for maintaining normal life, the adverse effects of hyperinsulinemia emphasize the importance of keeping insulin levels within a healthy range." (PMID 38339407, 2024). "Hyperinsulinemia is a higher than usual amount of insulin in the blood." (PMID 38397072, 2024). "It has been found that high dietary selenium intake may result in impaired insulin sensitivity as well as overexpression of GPx1 leading to dysregulated insulin secretion and hyperinsulinemia." (PMID 38877419, 2024). "Thus, insulin-resistant individuals promote renal tubular salt absorption due to compensatory hyperinsulinemia, leading to a state of salt overload and hypertension." (PMID 38783200, 2024). "Overall, this analysis indicates that succinate is associated with insulin secretion in humans, which may be particularly relevant to the hyperinsulinemia developed in insulin-resistant states." (PMID 38713514, 2024). "This association may stem from mechanisms such as insulin resistance, hyperinsulinemia, insulin promotion of LC growth, and the promotion of an inflammatory microenvironment." (PMID 39001440, 2024). "Also, d’Fonseca reported hyperinsulinemia along with higher insulin concentrations following an OGT in ponies fed to gain 27% of their body weight for 24 weeks but noted a consequentially more efficient glucose metabolism." (PMID 38473112, 2024). "The potential decreased hepatic clearance of insulin also contributes to hyperinsulinemia." (PMID 38473112, 2024). "Thus, to better understand the mechanism by which dietary 4-STN attenuated hyperinsulinemia, future studies are needed to evaluate the expression of proteins related to ER stress, insulin signaling, and gluconeogenesis in the liver and muscle." (PMID 38921456, 2024).
Hyperinsulinemia (continued). "Furthermore, a subgroup of individuals with MASLD presented a lipid-induced impairment of hepatic sensitivity, not only to insulin but also to glucagon, resulting in both hyperglucagonemia and hyperinsulinemia." (PMID 39459592, 2024). "In addition, in clinical studies, insulin therapy can lead to an increase in body fat percentage, and iatrogenic hyperinsulinemia can also induce hypertension, abnormal lipid metabolism and atherosclerosis, which are risk factors for ED." (PMID 39247921, 2024). "As previously detailed in the studies focused on the effects of hyperinsulinism or hyperandrogenism on FF, chemerin may act as an insulin or androgen mediator and may have an autocrine/paracrine effect in the ovarian environment, impairing ovary functioning." (PMID 39767764, 2024). "A longer duration of dysregulation of insulin secretion in infants with perinatal stress-induced hyperinsulinism may be due to a more profound and longer duration of fetal hypoxemia." (PMID 38792494, 2024). "Loss-of-function mutations cause persistent and unregulated insulin secretion and congenital hyperinsulinism, whereas gain-of-function mutations prevent KATP channel closure in response to glucose metabolism, resulting in a failure of insulin secretion and neonatal diabetes." (PMID 38366195, 2024). "While some HNF4A variants are known to cause congenital hyperinsulinism in the neonatal period, the patient was not overweight at birth nor hypoglycemic, suggesting insulin hypersecretion." (PMID 38745825, 2024). "Therefore, it was concluded that endogenous hyperinsulinism was unlikely; however, the possibility of insulin autoantibody syndrome needed to be excluded." (PMID 38926797, 2024). "Recent evidence also supports the hypothesis that reduced insulin sensitivity and hyperinsulinemia are among the most important factors contributing to kidney damage." (PMID 38139229, 2023). "Hyperinsulinemia is technically not just referring to the loss in glycaemia management as seen in “insulin resistance”, as insulin resistance is the term given when viewing insulin in the context of glucose regulation." (PMID 37760052, 2023). "We show that hyperinsulinemia is sufficient to increase cortical ceramide content, which has deleterious effects on mitochondrial bioenergetics, and that inhibiting ceramide synthesis is sufficient to reverse these insulin-induced changes." (PMID 38068958, 2023). "In cancer patients (without diseases associated with hyperinsulinemia), serum insulin levels have been reported to be elevated." (PMID 37958310, 2023). "Firstly, IR promotes insulin secretion, leading to hyperinsulinemia and increased BMD." (PMID 37705037, 2023). "Lower insulin levels in CSF can be due to prolonged hyperinsulinemia." (PMID 37372995, 2023). "Also, studies have reported that HF diet-induced hyperinsulinemia can impair the synaptic plasticity, neuronal survival, learning, and memory by affecting the insulin signaling in the central nervous system." (PMID 36810115, 2023). "Insulin sensitivity was inversely associated with serum sclerostin in obese women; hyperinsulinemia did not affect serum sclerostin in both lean and obese women." (PMID 37569816, 2023). "Moreover, hyperinsulinemia can reduce the urinary excretion of uric acid since insulin stimulates the urate-anion exchanger and/or the sodium-dependent anion co-transporter in the brush border membranes of proximal tubules." (PMID 38139229, 2023). "We have previously demonstrated that hypercarnitinemia combined with hyperinsulinemia (achieved via intravenous infusion of insulin [105 mU·m−2·min−1] for 6 h) also increased plasma carnitine clearance by ∼15% and resulted in an increase in skeletal muscle total carnitine content of ∼15%." (PMID 36806708, 2023). "Emerging evidence suggests that not only pancreatic insulin secretion, but also lower hepatic insulin clearance, may contribute to hyperinsulinemia (=increased peripheral insulin levels)." (PMID 36901984, 2023).
Hyperinsulinemia (continued). "When hyperinsulinemia occurs, such as pancreatic β-cell tumors and the rare insulin autoimmune syndrome, the insulin level and C-peptide level increase simultaneously, and the ratio of insulin to C-peptide (I:C) is still less than one." (PMID 38250973, 2023). "Future studies could address whether chronic hyperinsulinemia can also be reconstituted: if so, this could provide additional opportunities to assess insulin signaling adaptation in target organs." (PMID 36730473, 2023). "Lifestyle interventions reduce both insulin levels and inflammation, highlighting the likelihood that hyperinsulinemia and chronic inflammation act together to alter ovarian steroidogenesis, increase androgen levels, impair follicular development, and reduce ovulation." (PMID 37109585, 2023). "However, the vitamins C and E administered group showed a significant reduction in the serum insulin level, which suggests that vitamins C and E lower the glyphosate-induced hyperinsulinemia." (PMID 38274944, 2023). "In obese NL and obese NAFLD, hyperinsulinemia after glucose intake is caused by an increase in insulin secretion, without a decrease in overall hepatic or extrahepatic insulin extraction." (PMID 37189715, 2023). "Prolonged hyperinsulinemia could indicate there was a decrease in insulin sensitivity, which explains the tendency for glucose AUC to be higher in bromocriptine treated steers than in those not treated with bromocriptine." (PMID 37143501, 2023). "In addition to the expected differences in blood insulin, participants with delayed hyperinsulinemia also had sustained elevated blood glucose concentrations at the end of the OGTT curve (i.e., 90 and 120 min) and higher HOMA-IR scores." (PMID 37242230, 2023). "In the present study, decreases in liver and muscle insulin sensitivity were completely compensated by increased serum insulin concentration (SSSI) due to a decrease in insulin clearance (MCRI) and an increase in endogenous insulin secretion (SSSC) during hyperinsulinemia." (PMID 37373776, 2023). "Consumption of high glycemic index foods, such as cereals, confectionery, and sugar-sweetened beverages, is associated with a rapid release of carbohydrate, an increase in plasma glucose, and an increase in insulin secretion, leading to postprandial hyperinsulinemia, which has a lipogenic effect." (PMID 37242120, 2023). "The central paradox in the pathophysiologic association between hyperinsulinemia and hyperandrogenemia in PCOS is that the ovary remains sensitive to insulin activity and subsequent androgen production, despite a systemic state of IR, setting the stage for the “selective insulin resistance” theory." (PMID 37791160, 2023). "Pedersen’s hypothesis is that elevated maternal blood sugar levels can cross the placenta and stimulate the secretion of insulin by fetal islet cells, leading to hyperinsulinemia." (PMID 37328759, 2023). "However, in the case of hyperglycemia, hyperinsulinemia, and subsequent insulin resistance, the insulin-mediated inhibition of lipolysis in adipocytes is impaired." (PMID 37842470, 2023). "Future studies should also assess insulin secretion in isolated islets ex vivo to determine whether β-cell dysfunction is driving the observed hyperinsulinemia in vivo." (PMID 37115651, 2023). "In summary, the decline in insulin sensitivity due to the low or moderate weight gain can be compensated by increased β-cell function and β-cell mass and resulting hyperinsulinemia, whereas a more pronounced increase in body weight cannot be compensated and results in T2D." (PMID 38026205, 2023). "However, prolonged exposure to hyperinsulinemia would likely break this system if immune cells themselves became resistant to the action of insulin." (PMID 36992811, 2023). "It has been hypothesized that hyperinsulinemia, induced by the IR status, contributes to hyperandrogenism, since insulin may enhance both ovarian and adrenal steroidogenesis." (PMID 37256493, 2023).
Hyperinsulinemia (continued). "Aging mice with the deficiency had higher antioxidant activity, suggestive of increased hepatic oxidative stress, and developed hepatic steatosis with elevated alanine aminotransferase, basal hyperinsulinemia, increased insulin after glucose tolerance test, and reduced tolerance to insulin." (PMID 37107346, 2023). "Moreover, the levels of TNF-α expression strongly correlate with hyperinsulinemia and decreased insulin sensitivity." (PMID 37215099, 2023). "In addition, all these studies point to an important role of reduced hepatic insulin clearance as the potential culprit in the development of (peripheral) hyperinsulinemia." (PMID 36901984, 2023). "The activation of endothelial nitric oxide synthase was significantly impaired in hyperinsulinemic cells following acute insulin stimulation, which supports the notion that hyperinsulinemia alters the regulation of molecular targets involved in cerebral blood flow." (PMID 37834116, 2023). "In our review, we shed some light on the role of insulin secretion from beta cells and insulin clearance that could offer additional insight into the development of hyperinsulinemia and its relationship to hyperandrogenemia." (PMID 36834549, 2023). "Our data corroborate this work suggesting that HBER cows may have a hyperinsulinemia condition due to high insulin levels." (PMID 36626404, 2023). "The reproductive dysfunctions may occur because of over-exposure of insulin to the ovaries, which is a characteristic feature of hyperinsulinemia." (PMID 38234930, 2023). "Increased liver phosphorylation of AKT has previously been associated with higher fasted plasma insulin levels and hyperinsulinemia in C57BL6 animals on a HFD, although no information about substrain, vendor or sex was provided." (PMID 37531359, 2023). "Firstly, IR promotes insulin secretion, and hyperinsulinemia leads to an increase in BMD." (PMID 37258550, 2023). "Notably, the average baseline fasting insulin levels for all participants indicated a moderate state of hyperinsulinemia, with an average insulin level of 7.9 ± 7.2 mIU/L." (PMID 38140310, 2023). "Thus, isolated effects of glucose and insulin variations cannot be fully disjointed and it is conceivable that the observed general suppression of inflammatory markers is partly attributable to hyperinsulinemia." (PMID 37400734, 2023). "Ligand-activated GPCRs enhance insulin secretion through mechanisms that are either dependent or independent of the blood glucose level, thus leading to condescending hyperinsulinemia and β-cell failure." (PMID 37188647, 2023). "In conclusion, nutritional supplements in the form of a capsule with sporulated probiotic (BC-30) orally administered for 3 months improved glucose metabolism in AIP mice by reducing hyperinsulinemia and increasing glucose uptake in insulin-sensitive tissues (especially muscle)." (PMID 37569315, 2023). "Diets high in GI and GL could lead to chronic hyperinsulinemia and insulin suppresses IGFBP concentrations; in an Italian case-control study, ovarian cancer was inversely related to IGFBP, in particular to IGFBP-3." (PMID 37221355, 2023). "Interestingly, the same method demonstrated the presence of hyperinsulinemia in lean PCOS patients with normal insulin sensitivity, and even higher insulin secretion in lean patients than in obese patients or controls." (PMID 36834549, 2023). "Additionally, hyperinsulinemia is a compensatory reaction of pancreatic beta cells to a decrease in tissue sensitivity to the action of insulin." (PMID 36864815, 2023). "Interestingly, only HFD feeding induced hyperinsulinemia, and plasma insulin levels were only marginally enhanced by HGD feeding (P < 0.01)." (PMID 37399524, 2023). "Nonetheless, whether immune cells become insulin resistant with longstanding exposure to hyperinsulinemia and inflammatory stimuli is only beginning to be addressed." (PMID 36992811, 2023).
Hyperinsulinemia (continued). "It is conceivable that reduced zinc accumulation in insulin granules due to specific ZnT8 deficiency of β-cells does not lead to hyperinsulinemia because hepatic clearance of pancreatic hormone is increased." (PMID 38260166, 2023). "A recent report showed that the rapid onset of hepatic steatosis, adipose tissue hypertrophy, and hyperinsulinemia by ingestion of a HF–HS diet may be due to the rapid response of insulin signaling, lipogenesis, and inflammatory genes." (PMID 36830016, 2023). "A case report of cardiac hypertrophy in an exceptionally low BW newborn who received insulin therapy after developing chronic hyperglycemia due to parenteral nourishment supports the concept that iatrogenic hyperinsulinemia plays a role in the development of HCM." (PMID 37553638, 2023). "Despite numerous studies investigating the relationship between excess weight, decreased insulin sensitivity, and hyperinsulinemia in women with PCOS, our understanding of this multidirectional and synergistic web of interactions remains unclear." (PMID 36834549, 2023). "In diabetic rats, both basal and glucose-stimulated (120 min after glucose loading) levels of insulin and leptin also increased, indicating the development of hyperinsulinemia, hyperleptinemia, and resistance to insulin and leptin, which are characteristic features of DM2." (PMID 37108424, 2023). "Furthermore, reduced glucose tolerance, fasting hyperinsulinemia, and impaired glucose-stimulated insulin release were observed in WD fed mice." (PMID 36997560, 2023). "In addition, the degree of hyperinsulinemia was correlated with the severity of laminitis and was predicted for previous episodes in animals with elevated insulin levels." (PMID 37628596, 2023). "Proper insulin signaling relies on the regulated internalization of insulin bound to the insulin receptor, a process which is disrupted by hyperinsulinemia via an unknown mechanism." (PMID 37834116, 2023). "Hyperinsulinemia stimulates the production of ovarian androgens through its effects on the fully functional post-receptor MAP-K insulin pathway, and insulin also suppresses the hepatic production of SHBG, thereby accounting for the suppressed serum levels of SHBG in PCOS." (PMID 37361535, 2023). "If we accept the hypothesis that insulin is the primary driver, preventing hyperinsulinemia would be an important public health goal." (PMID 36823293, 2023). "Measuring fasting serum insulin (FINS) levels and differentiating between the two types of hyperinsulinemia might provide us with useful information to tailor the treatment regimens of patients receiving either insulin or insulin analog treatment." (PMID 37324170, 2023). "However, higher serum insulin concentrations completely compensated for impaired insulin sensitivity via decreased insulin clearance and increased endogenous insulin secretion during hyperinsulinemia." (PMID 37373776, 2023). "In addition, PP has been reported to improve insulin sensitivity by improving the effectiveness of liver insulin receptors, which suppresses the downregulation of insulin receptors induced by hyperinsulinemia." (PMID 37334299, 2023). "However, at later ages, this compensatory mechanism breaks down, leading to decreased insulin clearance and increased hyperinsulinemia." (PMID 38068822, 2023). "Some relevant studies to date have already suggested the idea that hyperinsulinemia and IR may represent two distinct features of the insulin metabolism dysregulation in PCOS." (PMID 36834549, 2023). "In the state of IR, the effect of insulin on the inhibition of fat degradation is diminished, and free fatty acids are further activated by serine kinase, thus aggravating the degree of IR and leading to hyperinsulinemia." (PMID 37537560, 2023).